PKD1 (polycystin 1, transient receptor potential channel interacting)
Diseases named in the same sentence as PKD1 in open-access papers (continued):
Sharing a sentence is not in itself a finding about the gene and the disease.
cyst (continued). "In another pkd1 mouse model, the administration of metformin lowered the cystic index and showed modest effects on cyst growth without reverting cystogenesis." (PMID 40149611, 2025). "The interaction between the PKD1 and PKD2 gene products, polycystin-1 and polycys-tin-2, forms a complex involved in calcium signaling, which is crucial for tubular structure maintenance and cyst development." (PMID 39451240, 2024). "Consistent with the decrease in cyst formation, Pkd1–/–C3–/–mice showed lower kidneys/body weight ratios and normal blood urea nitrogen (BUN) values." (PMID 38912583, 2024). "The effectiveness of HL156A in inhibiting cyst growth and improving renal function was confirmed by measuring the number of cysts and blood urea nitrogen (BUN) levels in the collecting duct-specific Pkd1 KO mice." (PMID 39062520, 2024). "The knockout of SMYD3 delayed cyst growth and improved kidney function in postnatal day 7 (P7) DKO kidneys compared to age-matched PKD1 single knockout (PKD1 SKO) kidneys, as shown by the decrease in the kidney-weight-to-body-weight (KW/BW) ratio, cystic index, and blood urea nitrogen (BUN) levels." (PMID 38540216, 2024). "Experiments using mouse models with either PKD1 or PKD2 inactivation have revealed that the absence of cilia hinders cyst growth throughout all segments of the nephron." (PMID 38254980, 2024). "Pathogenic variants in DNAJB11 are associated with cyst formation without kidney enlargement, but in contrast to ADPKD due to PKD1 or PKD2 mutations, also demonstrate chronic interstitial fibrosis." (PMID 38707833, 2024). "Absence of Glis2 resulted in significant protection from cyst growth following Pkd1 inactivation as indicated by significant improvements in kidney-to-body weight ratio, cystic index and BUN levels." (PMID 38693102, 2024). "Consistently, it was shown that simultaneous knockout of Fjx1 decelerates renal fibrosis, alleviates renal inflammation, and preserves renal function in mice with Pkd1 deletion; however, Fjx1 knockout did not markedly inhibit cyst formation." (PMID 38671465, 2024). "Screening of 247 protein kinase inhibitors in a live imaging assay identified UCN-01, UCN-02, I κ B kinase (IKK) inhibitor VII, and quinazoline as inhibiting cyst formation in PKD1−/− and PKD2−/− kidney organoids without adversely affecting organoid growth." (PMID 37146581, 2023). "In PKD1 knock out mouse models, FAK inhibitors delay cyst formation and improve renal function." (PMID 38039285, 2023). "We previously reported that unilateral nephrectomy increases the number of kidney resident macrophages (MФ) and pro-inflammatory cytokines, accelerating cyst progression in mice lacking Pkd1 (Pkd1KO)." (PMID 37538309, 2023). "Moreover, demethylation of an ADPKD cell line (WT 9–12) resulted in increased PKD1 expression, and treatment with a DNMT inhibitor repressed the cyst growth of the MDCK cyst-forming cell line." (PMID 35865176, 2022). "Treatment of UB organoids with the natural cAMP ligand vasopressin resulted in efficient cyst formation in PKD−/− but neither in PKD1+/− nor in wild-type UB or in nephron organoids." (PMID 36120564, 2022). "Additionally, the Class III HDAC SIRT1, was also upregulated in Pkd1 mutant mouse cells and kidneys to promote cyst growth and treatment with the SIRT1-specific inhibitor, EX-527, reduced cyst growth in Pkd1 mouse models." (PMID 35847973, 2022). "Anti-miR-17, but not antimiR-18, anti-miR-19 or anti-miR-25 LNAs, attenuated cyst growth in Pkd1 knock-out mice." (PMID 36120538, 2022). "In line with previous studies, subsequent differentiation of corrected and non-corrected PKD1 hiPSCs lines towards kidney organoids showed a low incidence of spontaneous cyst formation in patient derived kidney organoids." (PMID 36120564, 2022).
cyst (continued). "The cyst-reducing effect of RGLS4326 was present but blunted in Pkd1RC∆17/- or Pkd1RC/-; Pkd2∆17/∆17 cell lines, suggesting that this compound mediates its benefits in Pkd1RC/- cells primarily via Pkd1/2 derepression." (PMID 35965273, 2022). "As a sign that the miR-17-mediated PKD1 inhibition may even be relevant in individuals with ADPKD, we noted that deleting the PKD1 miR-17 motif in primary human ADPKD cultures increases PC1, and reduces 3D cyst growth and proliferation." (PMID 35965273, 2022). "In contrast, activation or downregulation of Hh signaling did not affect cyst formation in a Pkd1 mouse model." (PMID 34055783, 2021). "In Pkd2–/– mice aged to allow for cyst formation, chronic administration of an oral dopamine antagonist slowed renal cyst formation; this did not occur in Pkd1–/–, which retained intact GTB in the precystic state." (PMID 33886508, 2021). "However, treatment with cystic cell EVs/exosomes did not induce tubule dilation and cyst formation in 3-month-old wild-type mouse kidneys, suggesting that when both Pkd1 wild-type alleles present this treatment did not result in the levels of Pkd1 to reach the cystic threshold in vivo." (PMID 34315885, 2021). "They demonstrated that blebbistatin, a specific inhibitor of nonmuscle myosin II, induced a significant increase in cyst formation of PKD1-mutant kidney organoids, which provides an important clue for the development of new treatments for PKD36." (PMID 34654880, 2021). "To further investigate whether SCH23390 reduction in cyst formation may relate to its impact on flow-dependent transport, we studied the effect of SCH23390 on cyst formation in Pkd1–/– in which flow effect is intact." (PMID 33886508, 2021). "Notably, deletion of Pkd1 results in upregulation of hypoxia-inducible factor (HIF)-1α, which worsens cyst formation." (PMID 32859916, 2020). "Three of these compounds, Bosutinib, Vermurafenib and the CFTR inhibitor IOWH-032, which equally reduced the viability of both wt and Pkd1-null cell types (as ΔAUC did not pass the cutoff), reduced cyst formation." (PMID 32144367, 2020). "Indeed, Pkd1 KO mice injected with DCVC, which reached ESRD faster, had a shorter phase of cyst growth and displayed mainly small cysts at kidney failure." (PMID 31038742, 2019). "CTGF might also be increased downstream of transforming growth factor β signalling, which is increased during cyst expansion and fibrosis in more advanced stages of PKD in Pkd1-mutant mouse models and in humans with autosomal dominant PKD (ADPKD)." (PMID 31086050, 2019). "Metformin was shown to suppress cyst growth and fluid secretion through the inhibition of mTOR and CFTR in a previous study using MDCK cell cysts, mouse embryonic kidney explant cultures, and Pkd1 mouse models." (PMID 28769124, 2017). "Perhaps ectopic Shh expression in non-dilated tubules has not been appreciated in other models (e.g. homozygous Pkd1 or Pkd2 mutants) due to early and rapid cyst progression making it difficult to assess non-dilated tubules." (PMID 27853247, 2016). "Unexpectedly, we found that Col1a1(3.6)-Cre was not bone specific and resulted in deletion of Pkd1 in multiple tissues, leading to cyst formation in the kidney and pancreas, but not the liver of adult mice." (PMID 23029375, 2012). "Deletion of Pkd1 in mesenchymal precursors resulted in pancreatic and renal, but not hepatic, cyst formation." (PMID 23029375, 2012). "In the case of human ADPKD, two studies have described global gene expression changes in Pkd1-related cyst formation using cells derived from non-cystic/cystic human kidneys." (PMID 23209428, 2012). "In support of this, a recent report focused on the dynamics of cyst formation by utilizing an inducible Pkd1 mouse model, demonstrated that proliferation was not appreciably higher in cystic specimens than in aged matched controls." (PMID 18721488, 2008).
cyst (continued). "Glis2 and PC2 protein expression in Pkd1;Tulp3 double knockout cells remained unchanged from non-knockout controls further supporting the strict correlation of Glis2 levels in vitro with polycystin-dependent cyst forming potential in vivo." (PMID 38693102, 2024). "Finally, while not a feature of human ADPKD, significant sex dimorphism in cyst growth in Pkd1 adult mouse models has been described with female mice showing slower disease progression." (PMID 38693102, 2024). "Some suggest that PKD1 deletion in mice alters the biomechanical properties of the renal tubular basement membrane in a cilia-dependent manner, leading to distal tubular dilation and cyst formation, independent of cell proliferation." (PMID 39451240, 2024). "In addition, the double-knock-out mouse for Pkd1 and Mcp1 showed a significantly decreased rate of cyst growth and improved kidney function suggesting a substantial role of MCP1 in macrophage-mediated cyst growth." (PMID 36342644, 2023). "Lack of cyst growth with CB-839 in our global Pkd1KO mice may also be due to inhibiting extrarenal sources of Pkd1 that could contribute to cyst size, unlike the kidney specific mice." (PMID 37538309, 2023). "Alternatively, Tulp3 could additionally regulate a cCDCA signal during development, but fast cyst progression in absence of Pkd1 could make such regulation difficult to detect." (PMID 35832738, 2022). "Previous studies showed that early inactivation of the Pkd1 gene (before p12) triggers rapid development of polycystic disease (cystic window), whereas inactivation after p14 leads to late cyst formation after 4–5 months, with a mild phenotype (non-cystic window)." (PMID 35203500, 2022). "This genetic epistasis between Tulp3 and Pkd1 implied that some TULP3 ciliary cargoes suppress cystogenesis independently of polycystins during kidney development and that dysregulation of these signals may significantly contribute to the cyst growth in ADPKD." (PMID 35832738, 2022). "Kidney-tubule-specific Mettl3 overexpression induced the occurrence and enlargement of tubular cysts, and conversely, Mettl3 deletion attenuated cyst growth in three different orthologous ADPKD transgenic mouse models, irrespective of the type of PKD1 mutation or dynamics of cyst growth." (PMID 35865176, 2022). "The results obtained here showed that GA strongly inhibited MDCK cyst enlargement by inhibiting MDCK and Pkd1 mutant cell proliferation, which could suppress phosphorylation of the ERK1/2 and mTOR/S6K signaling pathways, as well as activate AMP-activated protein kinase." (PMID 35744960, 2022). "We similarly tested whether these two ACLY inhibitors could reduce cyst area in IMCD-derived Pkd1−/− (ID1-3E5) cells grown in 3D Matrigel cultures treated with IBMX and forskolin and found that BA and SB-204990 both significantly reduced cyst size compared with vehicle (DMSO)." (PMID 36504724, 2022). "The Pkd1 HET mice developed normally with no cyst formation in the kidneys for up to just over one year old, whereas renal cysts initiated at or around postnatal days 8–9 and cysts were extensively developed at postnatal day 21 in the kidneys from Pkd1 HOMO mice." (PMID 36611841, 2022). "A later study found the opposite, that Pkd1 loss activated JNK signaling, while Pkd1 overexpression repressed JNK activity Reports of JNK activity in cystic tissues are also conflicting, and no follow-up studies established JNK’s role in cyst formation." (PMID 34962918, 2021). "In contrast, SCH23390 did not prevent cyst formation in Pkd1–/– mice." (PMID 33886508, 2021).
cyst (continued). "Furthermore, the treatment of Pkd1 lacking embryos in mouse model with the Sirtuin-1 inhibitor EX-527 or nicotinamide was leading to slower cyst growth in these animals." (PMID 32847032, 2020). "Of the four ADPKD patients with no mutation detected in PKD1, PKD2, or any cyst-pathway gene, two were at CKD stage 5 but had small atrophic kidneys (P2 and P9), one was at stage 3 with typical ADPKD features (P4), and one had very mild disease with CKD stage 1 at age 74 (P8)." (PMID 31488014, 2019). "Indeed, treatment with the GLS inhibitors CB-839 resulted in a certain degree of reduction of cyst burden in two models of Pkd1 mutants, while it failed to improve the phenotype in a third one22." (PMID 30480096, 2018). "When Pkd1 is deleted on P1, cyst growth does not initiate until day 14–18." (PMID 27356569, 2016). "In this study, we present for the first time that TNFα regulates the expression and nuclear translocation of Id2 in renal epithelial cells, suggesting that cyst fluid TNFα may contribute to the upregulation and increased nuclear ld2 in ADPKD kidneys and Pkd1 mutant mouse kidneys." (PMID 26110849, 2015). "Hematoxylin-eosin (H&E)-stained sections showed no cyst formation in liver tissues from all of three groups, in spite of 35% and 54% reduction in Pkd1 mRNA expression in heterozygous Col1a1(3.6)-Cre;Pkd1flox/+ and homozygous Col1a1(3.6)-Cre;Pkd1flox/flox mice, respectively." (PMID 23029375, 2012). "At E14.5, Pkd1-/- mutants do not exhibit any cyst formation." (PMID 21518438, 2011). "Therefore, TULP3 may regulate cCDCA in addition to the CLCI during development, but fast cyst progression in absence of Pkd1 could make such regulation difficult to detect." (PMID 35832738, 2022). "However, miR-182-5p inhibition could not slow cyst growth in Pkd2f/f:Aqp2-cre mice because Wasf2, Dock1, and Itga4 play significant roles in Pkd1 but not in Pkd2 conditional KO mice." (PMID 29074972, 2017). "Genetic tests are frequently negative for PKD1/PKD2, and total cyst volume and residual tissue volume do not increase the prognostic value of MRI in patients with these radiological characteristics." (PMID 39928271, 2025). "The electrogenic 2Cl−/H+ exchanger, CLC-5, is significantly up-regulated and shows remarkable co-localization with H+-ATPase on the apical membrane of cyst epithelia in various TSC mouse models, but not in Pkd1 mutant mice." (PMID 38731991, 2024). "Despite the reduction of cyst burden and macrophage infiltration, the elevated BUN levels in Pkd1-miR Tg mice were not improved after treatment with suramin." (PMID 35955634, 2022). "In the case of Pkd1 or Kif3a mice, there was no abnormality in flow-dependent regulation of PT transport, and SCH23390 had no salutary effect on cyst formation." (PMID 33886508, 2021). "It has been found that inactivation of Pkd1 or an essential IFT gene, tg737 (IFT88) in adult mice results in no cyst formation until months after deletion of either gene." (PMID 33886508, 2021). "However, kidney to body weight ratio, cystic index and cyst size of both LTL+ and AQP2 + cysts were not significantly different between Pkd1 cko and Dko female mice, unlike in males." (PMID 41474822, 2025). "Recent research has shown that elevated levels of STIM1 and IP3R contribute to cyst growth by increasing the cAMP levels and promoting Ca+2 release from the ER, as demonstrated using STIM1 knockdown and pkd1 knockout in an ADPKD mouse model compared to non-cystic controls." (PMID 40136708, 2025). "Further, mice (sex‐dependency was not evaluated) with nephron specific Pkd1 gene disruption have reduced BP and decreased NKCC2 expression before cyst formation, although it must be noted that polycystin‐1 biological actions can be distinct from those of cilia." (PMID 35274831, 2022). "Additionally, PKD1 patients present with more severe cysts than PKD2; however, this is likely due to development of cysts at an earlier age rather than an increase in cyst growth." (PMID 29479522, 2017).
cyst (continued). "The fact that some cysts in ADPKD tissue and Pkd1 mutant kidneys do not appear to upregulate mTORC1 and the small number of cysts in patients with TSC calls into question the essential role of the mTOR cascade in cyst formation." (PMID 26077033, 2015).
polycystic kidney disease (173 papers, 2005 to 2026). A usually autosomal dominant and less frequently autosomal recessive genetic disorder characterized by the presence of numerous cysts in the kidneys leading to end-stage renal failure. "Mutations in the PKD1 gene are the primary cause of type 1 PKD (polycystic kidney disease), accounting for 78%-85% of all PKD cases." (PMID 41659037, 2026). "Traditionally, localization of Pkd1/2 in tubular epithelial cells has been considered the common cause of polycystic kidney disease." (PMID 39899153, 2025). "One patient with ICM carried a truncating TTN variant and another patient with ICM and polycystic kidney disease carried a LP variant in PKD1, a gene from the MGH panel." (PMID 39910139, 2025). "PKD1 variants are implicated in polycystic kidney disease, as well as estimated glomerular filtration rate." (PMID 39975192, 2025). "The other 7 positive tests included amyloidosis (TTR, N = 3), Alport syndrome (COL4A3, N = 2), polycystic kidney disease (PKD1, N = 1), and susceptibility to ESRD (APOL1, N = 1)." (PMID 40126616, 2025). "The 7 other positive tests included amyloidosis (TTR, N = 3), Alport syndrome (COL4A3, N = 2), polycystic kidney disease (PKD1, N = 1), and susceptibility to end stage renal disease (APOL1, N = 1)." (PMID 40126616, 2025). "Regarding renal manifestations, extensive deletions affecting both the TSC2 gene and the adjacent PKD1 gene are closely linked to the occurrence of polycystic kidney disease." (PMID 40364023, 2025). "The feline PKD1 gene was analyzed to identify specific mutations that cause polycystic kidney disease." (PMID 39535393, 2024). "From a breeding and/or veterinary practice perspective, one example illustrating the potential consequences of a different category, is linked to polycystic kidney disease, associated with the PKD1:c.9882C > A variant." (PMID 39703406, 2024). "As a result, this assay has great potential and can be used as a new screening test for polycystic kidney disease in felines caused by PKD1 mutations." (PMID 39535393, 2024). "The majority of the patients with a pathologic result in genetic testing were positive for a pathogenic variant in the TSC2 gene, including five cases of contiguous gene deletion syndrome of TSC2 and PKD1 causing both polycystic kidney disease and TSC." (PMID 39726678, 2024). "This is different from that in polycystic kidney disease, which is mainly caused by mutations of PKD1 or PKD2." (PMID 38433557, 2024). "In this study, the patient suffered a polycystic kidney phenotype and two miscarriages due to PKD1 gene disruption caused by reciprocal translocation." (PMID 37953234, 2023). "Noteworthy, one patient with variants in polycystin-1 (PKD1) - who was diagnosed with polycystic kidney disease - had a previous SCeAD, followed by a SCoAD four years after the first dissection event." (PMID 37214559, 2023). "Biallelic PKD1 variants, including hypomorphic variants, can cause very early onset polycystic kidney disease (VEO-PKD)." (PMID 40225160, 2023). "Some have previously been associated with disease; for instance, a deletion in the PKD1 (p.Asn720IlefsTer17, rs757757289) has been reported to be associated with polycystic kidney disease." (PMID 37059828, 2023). "Three genes in EDS patients affect the kidney: the sodium chloride co-transporter SLC12A3 associated with Gitelman syndrome M263800, uromodulin UMOD associated with renal tubular disease M263800, and PKD1 associated with polycystic kidney disease M173100." (PMID 37504295, 2023). "Polycystic kidney disease is one of the most com-mon inherited kidney diseases.It is caused by mu-tation in either PKD1 or PKD2 genes, of which PKD1 ac-counts for 85%of the cases." (PMID 39077603, 2022). "Our study demonstrates that TL was shortened and TERRA expression levels in the DNA-attached fraction increased in autosomal dominant polycystic kidney patients with mutations in PKD1 and PKD2 compared to the control group." (PMID 36291168, 2022).